MC4R (melanocortin 4 receptor)
Diseases named in the same sentence as MC4R in open-access papers (continued):
Sharing a sentence is not in itself a finding about the gene and the disease.
brain diseases (1 paper, 2013). "Our findings provide new insights into the mechanisms underlying the activation of glial MC4R and open perspectives for new therapeutic strategies for the treatment of inflammation-mediated brain diseases." (PMID 23468969, 2013). "Recently, agonists of MC4R have emerged as promising candidates for the treatment of brain disorders." (PMID 23468969, 2013).
MC4R also shares sentences with these, for which no sentence is quoted: Alström syndrome (5 papers); heart disease (4); hyperlipidemia (3); hypogonadotropic hypogonadism (3); Onset (3); Parkinson disease (3); Adult onset (2); alcohol abuse (2); ciliopathies (2); Fat (2); hypogonadism (2); Impaired glucose tolerance (2); Lewis lung carcinoma (2); neuroblastoma (2); neurological disorders (2); osteoporosis (2); POMC deficiency (2); prediabetes (2); psoriasis (2); retinitis pigmentosa (2); schizophrenia (2); sexual dysfunction (2); Sleep apnea (2); abdominal aortic aneurysm (1); acne (1); acute myocardial infarction (1); autoimmune hyperthyroidism (1); biliary atresia (1); bipolar disorder (1); cerebral artery (1).
A further 52 diseases each share a sentence with MC4R in 1 paper.